SNHG20 (small nucleolar RNA host gene 20)
Synonyms: PRO0872; FLJ25582; DKFZp686L05235; SCARNA16HG; C17orf86; LINC00338; NCRNA00338
Gene: Long non-coding RNA gene on chromosome 17 (77,086,716 to 77,099,902, forward strand). Ensembl gene ENSG00000234912.
Gene Ontology:
Biological process: RNA processing
Cellular component: nucleolus
Diseases named in the same sentence as SNHG20 in open-access papers:
SNHG20 is named in the same sentence as 34 diseases in open-access papers, as found by Europe PMC text mining. Sharing a sentence is not in itself a finding about the gene and the disease. The quoted sentences say what the papers report.
hepatocellular carcinoma (15 papers, 2016 to 2024). A malignant tumor that arises from hepatocytes. "SNHG20 is an aberrant expression in various cancers and promotes the development and progression of tumors, such as hepatocellular carcinoma, ovarian cancer, colorectal cancer, and bladder cancer." (PMID 37538124, 2023). "SNHG20 expression in hepatoma cells is positively correlated with HBx protein, and HBx-SNHG20 is involved in regulating the proliferation and apoptosis of hepatoma cells." (PMID 34869051, 2021). "A number of proinvasion proteins such as ZEB1, ZEB2, N-CAD, and VIM are positively correlated with SNHG20, thus leading to stimulated cell cycle progression, proliferation rate, and migration capacity hepatocellular carcinoma and breast cancer." (PMID 32318335, 2020). "The SNHG20 is up-regulated in colorectal cancer, hepatocellular cancer, lung cancer, ovarian cancer, and breast cancer." (PMID 32318335, 2020). "SNHG20 was originally identified in hepatocellular carcinoma, localized to 17q25.2, and highly expressed in hepatocellular carcinoma, promoting hepatocellular carcinoma proliferation and migration, and was negatively correlated with patient prognosis." (PMID 30744670, 2019). "Small Nucleolar RNA Host Gene 20 (SNHG20) is a 2183 bp lncRNA, and its overexpression predicts poor prognosis in colorectal cancer and hepatocellular carcinoma." (PMID 28981099, 2017). "Small nucleolar RNA host gene 20 located at 17q25.2 was originally reported in hepatocellular carcinoma (HCC) and promoted the cell proliferation." (PMID 29113337, 2017). "Moreover, SNHG20 is up-regulated in hepatocellular carcinoma and can be used as an independent prognostic factor." (PMID 30744670, 2019). "Furthermore, SNHG20 was upregulated in hepatocellular carcinoma and, in an in vitro study, its suppression distinctly inhibited hepatocellular carcinoma cell proliferation, migration, and invasion." (PMID 27835598, 2016). "In addition, the expression level of lncRNA SNHG20 has been shown to be significantly upregulated in hepatocellular carcinoma and could promote the epithelial-to-mesenchymal transition (EMT)." (PMID 35790551, 2022). "Initially, SNHG20 was discovered in hepatocellular carcinoma (HCC) and has been proved to function as an oncogene in HCC." (PMID 32675944, 2020). "The lncRNA SNHG20 has been demonstrated to play oncogenic roles in many cancers, including oral squamous cell carcinoma, ovarian cancer, colorectal cancer (CRC), cervical cancer, lung cancer, glioma and hepatocellular carcinoma." (PMID 38886753, 2024). "Small nucleolar RNA host gene 20 (SNHG20), a novel 2183-nt in length lncRNA located at 17q25.2 on the consistent strand to SEC14-like lipid binding 1 gene, was originally identified in hepatocellular cancer." (PMID 30846486, 2019). "LncRNA small nucleolar RNA host gene 20 (GenBank Accession ID NR_027058.1), which belongs to the SNHG lncRNA family, was first reported in hepatocellular carcinoma (HCC)." (PMID 34282711, 2021). "Small nucleolar RNA host gene 20 (SNHG20, GenBank Accession ID NR_027058.1) localized at 17q25.2 is originally identified in hepatocellular carcinoma (HCC) and suggested to be overexpressed in 2 HCC cohorts and TGCA dataset." (PMID 27543107, 2016).
colorectal cancer (14 papers, 2016 to 2024). A primary or metastatic malignant neoplasm that affects the colon or rectum. "In addition, in colorectal cancer, high expression of SNHG20 is an important independent risk factor for colorectal cancer patients and silencing SNHG20 increases p21 mRNA and protein expression levels and reduced CyclinA1 expression." (PMID 30744670, 2019). "Further insights into the clinical and functional implications of SNHG20 and its regulated pathways may facilitate the identification of new diagnostic or predictive indicators and drug targets for colorectal cancer." (PMID 27543107, 2016). "SNHG1, SNHG3, and SNHG20 are predictive biomarkers for neuroblastoma, ovarian cancer, and colorectal cancer, respectively." (PMID 35686101, 2022). "SNHG1, SNHG3, SNHG20 have been separately proved to be a prognostic biomarker in neuroblastoma, ovarian cancer, and colorectal cancer." (PMID 31967298, 2020). "Subsequently, the oncogene function of SNHG20 was identified in human cancer, such as lung cancer, osteosarcoma, bladder cancer, gastric cancer, and colorectal cancer." (PMID 30846486, 2019). "Another study confirmed that SNHG20 expression was significantly up-regulated in colorectal cancer (CRC) and knockdown of SNHG20 suppressed CRC cell proliferation, invasion and migration, and cell cycle progression." (PMID 29113337, 2017). "The present study aims to explore the clinical significance of SNHG20 and its potential molecular mechanism in colorectal cancer (CRC)." (PMID 27543107, 2016). "Meanwhile, SNHG20 could promote colorectal cancer cell proliferation, migration and invasion via miR-495/STAT3 axis." (PMID 34836544, 2021). "Up to now, this is the first study about the roles of SNHG20 in human colorectal cancer." (PMID 27543107, 2016). "For example, SNHG5 affects cell proliferation, metastasis and migration of colorectal cancer through regulating miR-132-3p/CREB5 and SNHG20 promotes the tumorigenesis of oral squamous cell carcinoma via targeting miR-197/LIN28 axis." (PMID 30858762, 2019). "Up-regulation of SNHG20 has been validated in several kinds of tumors, including non-small-cell lung cancer, colorectal cancer, gastric cancer, and bladder cancer." (PMID 34836544, 2021).
ovarian carcinoma (12 papers, 2019 to 2025). A malignant neoplasm originating from the surface ovarian epithelium. "SNHG20 promotes cell proliferation and invasion by suppressing the expression of miR−217 in ovarian cancer." (PMID 41200835, 2025). "First, the expression of SNHG20 in 30 ovarian cancer tissues and their adjacent normal tissues was measured by qRT-PCR assay." (PMID 34302635, 2021). "Consistent with previous studies, we verified that the expression of SNHG20 was upregulated in ovarian cancer tissues and SKOV3 and A2780 cells." (PMID 34302635, 2021). "The results indicated that the expression of miR-217 was negatively correlated with SNHG20 in ovarian cancer tissues." (PMID 34302635, 2021). "The qRT-PCR data showed that SNHG20 expression was significantly higher in ovarian cancer cell lines (SKOV3 and A2780) than in HOSEpiC cell line." (PMID 34302635, 2021). "Knockdown of SNHG20 inhibited the proliferation and invasion of ovarian cancer cells, whereas SNHG20 overexpression promoted cell growth and invasion." (PMID 34302635, 2021). "The result showed that SNHG20 was overexpressed in ovarian cancer compared with that in adjacent normal tissues." (PMID 34302635, 2021). "Up-regulated SNHG20 promoted growth and invasion of ovarian cancer cells, while knockdown of SNHG20 inhibited cell proliferation and invasion." (PMID 34302635, 2021). "In ovarian cancer, SNHG20 promoted ovarian cancer progression via Wnt/β-catenin signaling or by regulating the proliferation regulators and epithelial-mesenchymal transition (EMT)-related proteins." (PMID 34302635, 2021). "MiR-217 was downregulated in ovarian cancer tissues and cells, and was negatively regulated by SNHG20." (PMID 34302635, 2021). "The present study was aimed to investigate the functions and mechanisms of SNHG20 in ovarian cancer." (PMID 34302635, 2021). "Then, SNHG20 expression in ovarian cancer cell lines (SKOV3 and A2780) and human ovarian surface epithelial cell line (HOSEpiC) were also determined by qRT-PCR assay." (PMID 34302635, 2021). "In agreement with our data, SNHG20 expression markedly increased in tumor tissues and promoted the malignant progression in laryngeal squamous cell carcinoma, epithelial ovarian cancer, and osteosarcoma." (PMID 34650970, 2021). "In short, these data indicated that SNHG20 regulated ovarian cancer cell proliferation and invasion." (PMID 34302635, 2021). "In this study, we aimed to explore the expression pattern, role, and potential functional mechanism of SNHG20 in ovarian cancer." (PMID 34302635, 2021). "A previous report indicated that small nucleolar RNA host gene 20 (SNHG20) was closely correlated with the development of ovarian cancer." (PMID 34836544, 2021). "Further researches have shown that SNHG20 knockdown inhibited ovarian cancer cell proliferation, migration, invasion, epithelial-mesenchymal transition and promoted cell apoptosis." (PMID 34302635, 2021). "In ovarian cancer, SNHG20 can activate WNT/β-catenin signaling pathway, which promotes cell proliferation." (PMID 32318335, 2020). "For example, knockdown of SNHG20 inhibits the expression of β-catenin, inhibits the Wnt/β-catenin signaling pathway, and increased the apoptosis of ovarian cancer cells." (PMID 30744670, 2019). "SNHG20 was upregulated in ovarian cancer tissues and cell lines." (PMID 34302635, 2021). "Furthermore, overexpression of miR-217 suppressed the proliferation and invasion and reversed the effect of SNHG20 in ovarian cancer cells." (PMID 34302635, 2021). "Therefore, exploring the downstream genes of SNHG20/miR-217 in ovarian cancer is the focus of our future work." (PMID 34302635, 2021). "Together, SNHG20 promoted the proliferation and invasion of ovarian cancer via suppressing miR-217." (PMID 34302635, 2021). "In addition, future investigations are needed to determine more specific functions of SNHG20/miR217 in ovarian cancer cells, such as their role in cell apoptosis." (PMID 34302635, 2021).
ovarian carcinoma (continued). "Overexpression of SNHG20 promoted ovarian cancer cell proliferation and invasion." (PMID 34302635, 2021). "Taken together, SNHG20 might play an important role in the cell proliferation and invasion of ovarian cancer." (PMID 34302635, 2021). "SNHG20 promoted cell proliferation and invasion by sponging miR-217 in ovarian cancer." (PMID 34302635, 2021). "However, the potential molecular mechanism of SNHG20 in ovarian cancer is unclear." (PMID 34302635, 2021). "However, the potential mechanism of SNHG20 in ovarian cancer is unclear." (PMID 34302635, 2021). "In addition, we investigated whether there were some relationships between SNHG20 expression and ovarian cancer stages." (PMID 34302635, 2021). "SNHG20 has been reported to be upregulated in serous epithelial ovarian cancer and induce the expression of E-cadherin by activating the Wnt/β-catenin pathway, subsequently promoting the proliferation, migration, and EMT ability of ovarian cancer cells." (PMID 41200835, 2025). "However, the functions of SNHG20 in epithelial ovarian cancer (EOC) are not well established." (PMID 30846486, 2019).
glioma (10 papers, 2019 to 2025). A benign or malignant brain and spinal cord tumor that arises from glial cells (astrocytes, oligodendrocytes, ependymal cells). "The function of ZRANB2/SNHG20/FOXK1 axis in glioma associated with vasculogenic mimicry formation was analyzed." (PMID 30744670, 2019). "The RNA-binding protein ZRANB2 directly interacts with SNHG20, enhancing its stability and increasing its levels within glioma cells." (PMID 40277941, 2025). "SNHG20 played a crucial role in the ZRANB2/SNHG20/FOXK1 axis to regulate vasculogenic mimicry of glioma." (PMID 34178684, 2021). "In summary, our study found for the first time that ZRANB2 and SNHG20 are up-regulated in glioma tissues and glioma cells." (PMID 30744670, 2019). "We further analyzed the nascent SNHG20 and half-life of SNHG20 in glioma cells treated with ZRANB2 knockdown and overexpression." (PMID 30744670, 2019). "The expression of SNHG20 in glioma tissues of different grades was up-regulated compared with NBTs and was positively correlated with pathological grade of glioma; the expression of SNHG20 in U87 and U251 was also increased compared with NHA." (PMID 30744670, 2019). "The expression of SNHG20 in glioma tissues as well as glioma cell lines U87 and U251 was detected by qRT-PCR." (PMID 30744670, 2019). "A previous study has shown that SNHG20 was markedly elevated in glioma cells, and inhibition of SNHG20 expression could increase the apoptosis of glioma cells." (PMID 34302635, 2021). "In the subgroup analysis according to cancer types, augmented SNHG20 expression was significantly related to poor OS in respiratory system cancers, gliomas, digestive system cancers, head and neck neoplasms as well as osteosarcomas, but not in cancers of the reproductive system." (PMID 32675944, 2020). "Consequently, ZRANB2 promoted VM formation in glioma cells at least by increasing the stability of SNHG20." (PMID 30744670, 2019). "Similarly, our study finds that SNHG20 is highly expressed in glioma tissues and cells, and knockdown of SNHG20 reduces VM of glioma by reducing the expression of VM-related molecular MMP1, MMP9, VE-Cadherin." (PMID 30744670, 2019). "The results suggest that SNHG20 plays as oncogenic role in gliomas." (PMID 30744670, 2019). "In addition, migration and invasion abilities of glioma cells in SNHG20(−) group was inhibited compared with SNHG20(−)-NC group, while enhanced in SNHG20 (+) group compared with SNHG20(+)-NC group." (PMID 30744670, 2019). "ZRANB2/SNHG20/FOXK1 axis plays an important role in regulating vasculogenic mimicry formation of glioma, which might provide new targets of glioma therapy." (PMID 30744670, 2019). "In addition, transfection with FOXK1(−) could rescue the inhibitory effect of SNHG20(−) on proliferation, migration, invasion and VM of glioma cells, while FOXK1(+) could rescue the promoting effect of SNHG20 (+) similarly." (PMID 30744670, 2019). "It has been reported that the ZRANB2/SNHG20/FOXK1 axis plays a crucial role in regulating VM formation in the U87 and U251 glioma cell lines." (PMID 40277941, 2025). "SNHG20, which is stabilized by zinc finger RANBP2-type containing 2 (ZRANB2), maintains the stability of forkhead box K1 (FOXK1) mRNA to accelerate glioma progression." (PMID 38886753, 2024). "ZRANB2 was also overexpressed in glioma cells and tissue, being a part of the ZRANB2/SNHG20/FOXK1 axis which was essential in regulating the vasculogenic mimicry formation of glioma." (PMID 34482648, 2021). "RBP-ZRANB2 is overexpressed in glioma cells, knockdown of ZRANB2 inhibits the ability of VM formation in glioma cells through SNHG20/FOXK1 pathway." (PMID 33542193, 2021). "The expression of ZRANB2, SNHG20 and FOXK1 in glioma were detected by real-time PCR or western blot." (PMID 30744670, 2019). "This study first examined the endogenous expression of ZRANB2, SNHG20 and FOXK1 in glioma tissues and U87 and U251 glioma cells, and studied the effects of ZRANB2, SNHG20 and FOXK1 on VM formation in glioma." (PMID 30744670, 2019).
glioma (continued). "This study demonstrates for the first time that SNHG20 promotes the degradation of FOXK1 mRNA through the SMD pathway and regulates the VM formation in gliomas." (PMID 30744670, 2019). "Co-transfection of SNHG20(−) cells with FOXK1(+) strongly decreased the expression of MMP1, MMP9, VE-Cadherin and strongly inhibited the abilities of proliferation, migration, invasion and VM of glioma cells." (PMID 30744670, 2019). "This study demonstrated that the ZRANB2/SNHG20/FOXK1 axis played an important role in regulating the expression of VM-related molecules MMP1, MMP9 and VE-Cadherin, and regulated the VM formation of glioma." (PMID 30744670, 2019). "In addition, transfection with SNHG20(+) could rescued the inhibitory effect of ZRANB2(−) on proliferation, migration, invasion and VM of glioma cells, while SNHG20(−) could rescued the promoting effect of ZRANB2(+) similarly." (PMID 30744670, 2019). "Co-transfection of ZRANB2(−) cells with SNHG20(−) could strongly decrease the expression of MMP1, MMP9, VE-Cadherin and strongly inhibit the abilities of proliferation, migration, invasion and VM of glioma cells." (PMID 30744670, 2019).
non-small cell lung carcinoma (9 papers, 2017 to 2021). A group of at least three distinct histological types of lung cancer, including non-small cell squamous cell carcinoma, adenocarcinoma, and large cell carcinoma. "For instance, SNHG20 has been demonstrated to promote tumor growth through functioning as a competing endogenous RNA (ceRNA) of miR-154 in non-small cell lung cancer and modulating the expression of ZEB2 and RUNX2." (PMID 32675944, 2020). "The long non-coding RNA small nucleolar RNA host gene 20 (SNHG20) represses p21 in non-small lung cell cancer cells A549 facilitating proliferation and migration." (PMID 31438587, 2019). "Here, we found that SNHG20 was upregulated in non-small cell lung cancer (NSCLC) tissues compared with normal samples." (PMID 28981099, 2017). "Upregulating SNHG20 promotes cell proliferation and migration by epigenetically silencing of P21 expression through EZH2 in non-small cell lung cancers." (PMID 34811354, 2021).
esophageal squamous cell carcinoma (8 papers, 2019 to 2024). Esophageal squamous cell carcinoma (ESCC) is a type of esophageal carcinoma (EC) that can affect any part of the esophagus, but is usually located in the upper or middle third. "In esophageal squamous cell carcinoma, Small nucleolar RNA host gene 20 (SNHG20) promotes PD-L1 expression via ataxia telangiectasia mutated kinase (ATM)/JAK-PD-L1 pathway." (PMID 33194608, 2020). "Small nucleolar RNA host gene 20 (SNHG20) enhances PD-L1 expression in esophageal squamous cell carcinoma via the ATM/JAK/PD-L1 pathway." (PMID 36612180, 2022). "SNHG20 promotes tumorigenesis through the ATM-JAK-PD-L1 pathway in esophageal squamous cell carcinoma (ESCC)." (PMID 32042268, 2020). "Additionally, small nucleolar RNA host gene 20 (SNHG20) increases the expression of PD-L1, ataxia telangiectasia mutated kinase (p-ATM), and p-JAK1/2 in esophageal squamous cell carcinoma." (PMID 31850199, 2019). "LncRNA small nucleolar RNA host gene 20 (SNHG20) also plays a crucial role in increasing the expression of PD-L1, p-ATM, and p-JAK1/2 in esophageal squamous cell carcinoma." (PMID 34303380, 2021).
bladder cancer (7 papers, 2019 to 2024). "By activating this signaling pathway, lncRNA SNHG20 significantly promotes the malignant progression of bladder cancer." (PMID 38695942, 2024). "In bladder cancer, SNHG20 promotes bladder cancer cell proliferation and inhibits apoptosis through the Wnt/β-catenin pathway." (PMID 30744670, 2019). "The long non-coding RNA small nucleolar RNA host gene 20 (SNHG20) is located on 17q25.2, which has been reported to act as an oncogene in various tumors, such as prostate cancer, gastric cancer, bladder cancer, and lung cancer." (PMID 34302635, 2021). "In addition, SNHG20 promoted bladder cancer cell proliferation, colony formation, migration and invasion, and induced cell apoptosis, and SNHG20 was associated with advanced clinical stage, lymph node metastasis, and reduced patient survival rate of bladder cancer patients." (PMID 33089952, 2020).